LINC01443 (long independently transcribed non-coding RNA 1443)
Gene: Long non-coding RNA gene on chromosome 18 (14,946,267 to 14,974,215, forward strand). Ensembl gene ENSG00000266554.
Diseases named in the same sentence as LINC01443 in open-access papers:
LINC01443 is named in the same sentence as 1 disease in open-access papers, as found by Europe PMC text mining. Sharing a sentence is not in itself a finding about the gene and the disease. The quoted sentences say what the papers report.
cancer (1 paper, 2024). A tumor composed of atypical neoplastic, often pleomorphic cells that invade other tissues. "Finally, there is a subset of LINC01378, LINC01443, LINC01477, and LINC01544, which are typically represented in one or two pathways in only one cancer type." (PMID 38540157, 2024).